SLC38A5 (solute carrier family 38 member 5)
Diseases named in the same sentence as SLC38A5 in open-access papers (continued):
Sharing a sentence is not in itself a finding about the gene and the disease.
retinopathy (2 papers, 2022 to 2024). "Genetic deficiency of Slc38a5 in mice substantially delays retinal vascular development and suppresses pathological neovascularization in oxygen-induced retinopathy modeling ischemic proliferative retinopathies." (PMID 36454214, 2022). "Findings presented here suggest that modulation of SLC38A5 and its associated AAs may have translational value in treating retinopathy." (PMID 36454214, 2022). "This study establishes that AA transporter SLC38A5 is a new pro-angiogenic regulator in the retinal vascular endothelium both during development and in retinopathy." (PMID 36454214, 2022). "Targeting of AAs and their transporters such as SLC38A5 may thus represent a new potential approach to treat retinopathy via modulating EC AA transport and metabolism." (PMID 36454214, 2022). "In the late proliferative phase of retinopathy, however, inhibiting AA transporters like SLC38A5 or starving retinal vessels from AA nutrients may be beneficial in directly suppressing uncontrolled pathological neovascularization." (PMID 36454214, 2022). "Moreover, genetic deficiency of Slc38a5 impairs both developmental retinal angiogenesis and pathological retinal angiogenesis in a mouse model of oxygen-induced retinopathy (OIR), modeling proliferative retinopathies." (PMID 36454214, 2022). "Here our data suggest lack of SLC38A5, and likely subsequent impaired glutamine uptake, dampens developmental angiogenesis, in line with the pro-angiogenic role of AAs in the first phase of retinopathy." (PMID 36454214, 2022).
SLC38A5 also shares sentences with these, for which no sentence is quoted: Familial exudative vitreoretinopathy (2 papers); inflammation (2); bladder cancer (1); breast adenocarcinoma (1); breast invasive carcinoma (1); cervical cancer (1); chondrosarcoma (1); colon adenocarcinoma (1); depression (1); epilepsy (1); glioma (1); head and neck squamous cell carcinoma (1); infection (1); intestinal inflammation (1); neuroblastoma (1); neurological diseases (1); Obesity (1); retinopathy of prematurity (1).